INPP5E (inositol polyphosphate-5-phosphatase E)
Description:
Phosphatidylinositol (PtdIns) phosphatase that specifically hydrolyzes the 5-phosphate of phosphatidylinositol-3,4,5-trisphosphate (PtdIns(3,4,5)P3), phosphatidylinositol 4,5-bisphosphate (PtdIns(4,5)P2) and phosphatidylinositol 3,5-bisphosphate (PtdIns(3,5)P2) (By similarity). Specific for lipid substrates, inactive towards water soluble inositol phosphates. Can also remove the 5-phosphate from 1D-myo-inositol 1,4,5-trisphosphate (Ins(1,4,5)P3). Plays an essential role in the primary cilium by controlling ciliary growth and phosphoinositide 3-kinase (PI3K) signaling and stability (By similarity).
Synonyms: PPI5PIV; CORS1; pharbin; CPD4; JBTS1; MORMS
Tractability: Small molecule: it has a binding pocket of medium quality. Antibody: UniProt places it where antibodies can reach, with medium confidence; its Gene Ontology location is reachable by antibodies, with medium confidence. PROTAC: ubiquitination databases record sites on it; its protein half-life has been measured.
Gene: Protein-coding gene on chromosome 9 (136,428,618 to 136,439,882, reverse strand). Ensembl gene ENSG00000148384.
Subcellular location: Cytoplasm, cytoskeleton, cilium axoneme; Golgi apparatus, Golgi stack membrane; Cell membrane; Cell projection, ruffle; Cytoplasm; Nucleus
Subcellular location (Human Protein Atlas): Golgi apparatus; Focal adhesion sites; Nucleoplasm
Pathways (Reactome):
Metabolism: Synthesis of PIPs at the Golgi membrane
Organelle biogenesis and maintenance: ARL13B-mediated ciliary trafficking of INPP5E
Gene Ontology:
Molecular function: phosphatidylinositol-3,4,5-trisphosphate 5-phosphatase activity; phosphatidylinositol-4,5-bisphosphate 5-phosphatase activity; protein binding; inositol-polyphosphate 5-phosphatase activity; phosphatidylinositol-3,5-bisphosphate 5-phosphatase activity; inositol-1,4,5-trisphosphate 5-phosphatase activity; phosphatase activity; phosphatidylinositol-3,4,5-trisphosphate 3-phosphatase activity; phosphatidylinositol-4,5-bisphosphate phosphatase activity
Biological process: phosphatidylinositol biosynthetic process; phosphatidylinositol dephosphorylation; negative regulation of phosphatidylinositol 3-kinase/protein kinase B signal transduction; negative regulation of translation; phosphatidylinositol-3-phosphate biosynthetic process; phosphorus metabolic process
Cellular component: axoneme; cilium; cytosol; Golgi apparatus; nucleus; cytoplasm; Golgi cisterna membrane; Golgi membrane; plasma membrane; plasma membrane bounded cell projection; ruffle
Genetic constraint (gnomAD): Loss-of-function variants: 36 observed, 40.34 expected, observed/expected ratio (o/e) 0.89, 90% interval 0.68 to 1.18. The synonymous counts are far from expectation, so gnomAD's model fits this gene poorly and the ratio says little. Missense variants: 941 observed, 792.21 expected, observed/expected ratio (o/e) 1.19, 90% interval 1.12 to 1.25. Synonymous variants: 447 observed, 352.69 expected, observed/expected ratio (o/e) 1.27, 90% interval 1.17 to 1.37.
Gene-disease validity (ClinGen):
ClinGen rates the evidence that INPP5E causes each of these diseases.
Joubert syndrome 1 (autosomal recessive): Definitive. Any Joubert syndrome in which the cause of the disease is a mutation in the INPP5E gene.
MORM syndrome (autosomal recessive): Moderate. MORM syndrome is characterized by the association of intellectual deficit, truncal obesity, retinal dystrophy and micropenis.
Homologues: Orthologues: macaque INPP5E (98% identical), chimpanzee INPP5E (93% identical), rat Inpp5e (77% identical), mouse Inpp5e (77% identical), pig INPP5E (76% identical), guinea pig INPP5E (75% identical), dog INPP5E (72% identical), tropical clawed frog sec16a (55% identical), zebrafish inpp5e (50% identical), Drosophila melanogaster INPP5E (32% identical), Caenorhabditis elegans inpp-1 (16% identical). Paralogues in human: INPPL1 (22% identical), SYNJ1 (22% identical), SYNJ2 (22% identical), INPP5B (21% identical), INPP5D (20% identical), OCRL (19% identical), INPP5J (18% identical), INPP5K (14% identical), FIG4 (13% identical), INPP5F (13% identical), SACM1L (10% identical), SH2D1B (4% identical), and 1 more.
Diseases named in the same sentence as INPP5E in open-access papers:
INPP5E is named in the same sentence as 58 diseases in open-access papers, as found by Europe PMC text mining. Sharing a sentence is not in itself a finding about the gene and the disease. The quoted sentences say what the papers report.
ciliopathy (39 papers, 2012 to 2025). A genetic disorder of the cellular cilia or the cilia anchoring structures, the basal bodies, or of ciliary function. "Although further studies are needed to elucidate the mechanisms underlying the roles of INPP5E and develop restorative interventions for ciliopathies, some important findings have been published, as presented herein." (PMID 39781470, 2025). "INPP5E mutations are associated with various pathologies, including Joubert syndrome, human syndromic ciliopathies, mental retardation, truncal obesity, retinal dystrophy, and micropenis (MORM) syndrome 11-14." (PMID 39781470, 2025). "Mutations in INPP5E have been associated with various ciliopathies, including Joubert syndrome, which can present with glaucoma as one of the clinical features." (PMID 39337513, 2024). "Pathogenic variants in INPP5E hence cause a variety of ciliopathies: genetic disorders caused by dysfunctional cilia." (PMID 38806661, 2024). "Dysregulation of phosphoinositide in INPP5E-deficient mice results in the lethality of embryos and ciliopathies in humans." (PMID 37670137, 2023). "In humans, loss of Inpp5e function is associated with Joubert Syndrome, a multisystem ciliopathy characterized by organ dysfunction and cognitive impairment due to ciliary transition zone dysfunction." (PMID 37064917, 2023). "The mutation of INPP5E will cause deficiency of primary cilia signaling transduction, ciliary instability and ciliopathies." (PMID 35463949, 2022). "Two human ciliopathy syndromes are associated with INPP5E mutations: Joubert syndrome (JBTS) and MORM syndrome." (PMID 36547473, 2022). "INPP5E mutations can also cause other ciliopathies, including retinitis pigmentosa (RP), Leber congenital amaurosis (LCA), and MORM syndrome (mental retardation, obesity, retinal dystrophy, and micropenis in males)." (PMID 36063381, 2022). "Ciliopathies resulting from Inpp5e mutations can be considered consequences of the permanent activation of this PIP2-dependent ciliary fission pathway." (PMID 35079141, 2022). "Pathogenic variants in INPP5E can lead to a broad phenotypic spectrum ranging from severe ciliopathies to non-syndromic IRD9–11,17,24–26." (PMID 34188062, 2021). "INPP5E missense mutations of the phosphatase catalytic domain cause Joubert syndrome in humans—a syndromic ciliopathy affecting multiple tissues including the brain, liver, kidney, and retina." (PMID 33711342, 2021). "INPP5E mutations cause two human ciliopathy syndromes, namely Joubert syndrome (OMIM #213300) and MORM (mental retardation, obesity, congenital retinal dystrophy and micropenis in males; OMIM #610156)." (PMID 32970140, 2020). "In humans, hypomorphic INPP5E mutations contribute to Joubert Syndrome (JS), a ciliopathy characterized by cerebellar malformations and concomitant ataxia and breathing abnormalities." (PMID 32840212, 2020). "INPP5E is mutated in Joubert syndrome (JS), a ciliopathy characterized by cerebellar defects in which a subset of patients also shows malformations of the cerebral cortex including heterotopias, polymicrogyria and agenesis of the corpus callosum." (PMID 32840212, 2020). "In humans, variants in INPP5E are linked to recessively inherited ciliopathies, Joubert Syndrome 1 (JBTS1) and clinically a very different syndrome Mental retardation, Truncal obesity, Retinal dystrophy and Micropenis (MORM)." (PMID 30235266, 2018). "Interfering with any of these steps can provide valuable insights in studying the role of INPP5E in ciliopathies especially that a mutation which influences its localization to cilia is associated with MORM syndrome." (PMID 27063844, 2016). "Importantly, variants in INPP5E are associated with ciliopathies, including Joubert syndrome and syndromic and non-syndromic IRD." (PMID 40037334, 2025). "Thus, the phosphoinositide distribution regulated by INPP5E is closely associated with ciliopathies." (PMID 38514901, 2024).
ciliopathy (continued). "Similarly, mutations in Arl13b and Inpp5e cause ciliopathies that fall under Joubert Syndrome related disorders and lead to aberrant axonal tracts in mouse models that mimics human axonal tract defects." (PMID 37064917, 2023). "Indeed, it was reported in 2009 that mutations in an inositol polyphosphate 5-phosphatase, INPP5E, are causal for multiple ciliopathies." (PMID 36547473, 2022). "Importantly, mutations in the Inpp5e gene cause its loss-of-function due to mislocalization or impairment in catalytic activity and manifest in a ciliopathy termed Joubert syndrome (JBTS)." (PMID 33771931, 2022). "It was well tolerated, so clinical repurposing trials in ciliopathy patients with Inpp5e mutations could be considered." (PMID 35079141, 2022). "We hypothesise that a similar molecular mechanism mediates ciliary fission, ciliary disassembly in response to serum, vesicle budding induced by receptor activation, and the ciliopathy in Inpp5e-deficient cells." (PMID 35079141, 2022). "INPP5E is a ciliary phosphoinositide phosphatase mutated in ciliopathies like Joubert syndrome." (PMID 36063381, 2022). "Mutated Inpp5e has been reported in ciliopathies: MORM Syndrome and JBTS." (PMID 34093381, 2021). "Furthermore, genetic mutations in Arl13b and INPP5E are linked to the ciliopathy Joubert syndrome." (PMID 29244804, 2017). "Loss of INPP5E function is the underlying cause of two ciliopathies, Joubert syndrome and MORM syndrome, as well as ciliopathy phenotypes in mice and zebrafish, demonstrating the significance of phosphoinositide compartmentalization in cilia biology." (PMID 41064964, 2025). "INPP5E, a cilia-localized inositol 5-phosphatase whose malfunction leads to ciliopathies and phosphoinositide compartmentalization, which in turn ensures proper protein trafficking and Hedgehog (Hh) signaling at primary cilia." (PMID 38052787, 2023). "Overall, our work highlights the potential of INPP5E as a pan-treatment for ciliopathies, thus moving beyond single-gene replacement and benefitting a broader patient population." (PMID 35771640, 2022). "Apart from cranial NTDs, Inpp5e-knockout mice showed characteristics of ciliopathies, for instance polydactyly and polycystic kidneys." (PMID 34093381, 2021). "Inpp5e KO mice are embryonically lethal with a classical ciliopathy phenotype including exencephaly, anophthalmia, polydactyly, polycystic kidneys, pulmonary hypoplasia, cleft palate, oedema and ossification delays." (PMID 32970140, 2020). "Mutations in INPP5E cause Joubert and MORM (mental retardation, truncal obesity, retinal dystrophy, and micropenis) syndromes in humans, and Inpp5e knockout mice display phenotypes consistent with ciliopathies." (PMID 32850869, 2020). "Given that the functional interactors of ERICH3 are all associated with ciliary diseases such as Joubert syndrome (ARL13B, INPP5E) and Bardet Biedl syndrome, ERICH3 represents an attractive candidate for mutations in unresolved ciliopathies." (PMID 31712586, 2019). "The role of INPP5E in ciliopathy has been investigated using various animal and human models." (PMID 39781470, 2025). "This study shows that PIP4K2a as a kinase functions in opposite to INPP5E to contribute to ciliopathies, which may directly link phosphoinositide signaling to primary cilium stability." (PMID 38052787, 2023). "Ciliopathies associated with altered PIP2 distribution are not limited to INPP5E/JBTS but also occur in a similar disease of oculo-cerebro-renal syndrome of Lowe (OCRL)." (PMID 33771931, 2022). "Since almost all INPP5E ciliopathy mutations affect the catalytic domain, none were found near CLS1." (PMID 36063381, 2022). "We argue that this pathway is overactive in Inpp5e dependent ciliopathies." (PMID 35079141, 2022). "Pathogenic variants in INPP5E cause Joubert syndrome (JBTS), a ciliopathy with retinal involvement." (PMID 34188062, 2021).
ciliopathy (continued). "The hypothesis that this gene variant is the causative variant of HRFCD is supported by the known functional role of INPP5E in primary cilia and the malfunction of INPP5E results in ciliopathies." (PMID 30235266, 2018). "Finally it would be interesting to exploit available small molecules that inhibit the interaction of PDE6δ with farnesylated cargo in studying the role of INPP5E in cilia and ciliopathies." (PMID 27063844, 2016). "In this regard, it is interesting to note that PIP2 phosphatases, INPP5E and INPP5F, are localized in the cilia and their functional deficits are associated with ciliopathy, thus creating a potential gradient of PIP2 physiologically at the cilia-plasma membrane junction." (PMID 23351594, 2012). "Interestingly, the inactivation of Inpp5e in mice on the postnatal day-28 did not affect the survival of adult mice; however, still caused ciliopathy phenotypes such as higher body weight, retinal dystrophy, and cystic glomeruli." (PMID 36547473, 2022). "Besides its catalytic domain and C-terminus, INPP5E also contains a proline-rich N-terminal region, where no ciliopathy mutations have been reported." (PMID 36063381, 2022). "In addition to cranial NTDs, mice lacking Inpp5E exhibit features of ciliopathies such as polycystic kidneys and polydactyly, while mutations in INPP5E are found in the ciliopathies Joubert Syndrome and MORM Syndrome." (PMID 27324558, 2017). "Given the importance of PI signalling in ciliogenesis initiation identified here and the identification of various PI 5-phosphatases (such as INPP5E, INPP5B and OCRL) as causal loci for ciliopathies, we reason that PIPKIγ malfunction may also be correlated with ciliopathies." (PMID 26916822, 2016). "In control fibroblasts INPP5E was present in 82% of total cilia, and in the CED ciliopathy patient 74% of the total cilia were positive for INPP5E." (PMID 38806661, 2024). "Inositol phosphatase INPP5E contains a prenylation CAAX motif, which was found to play a role in MORM syndrome (a ciliopathy)." (PMID 23805271, 2013). "INPP5E deletion of CAAX domain has been reported in MORM syndrome, another ciliopathy with clinical similarities to Bardet-Beidel syndromes." (PMID 23805271, 2013).
Joubert syndrome (38 papers, 2006 to 2025). Joubert syndrome (JS) is characterized by congenital malformation of the brainstem and agenesis or hypoplasia of the cerebellar vermis leading to an abnormal respiratory pattern, nystagmus, hypotonia, ataxia, and delay in achieving motor milestones. "This has been observed in conditions like Parkinson`s disease, in nephronophthisis associated with CEP290 mutations in Joubert syndrome, and abnormal brain ventralization linked to dysfunctional INPP5E." (PMID 40483459, 2025). "Diseases linked to INPP5E mutations include Joubert syndrome, Leber congenital amaurosis, and MORM syndrome." (PMID 39781470, 2025). "Biochemical data from patients with Joubert syndrome has shown a missense mutation in INPP5E, which is associated with a reduced number of cilia and shorter ciliary length, indicating that INPP5E is essential for cilia formation and function." (PMID 39781470, 2025). "Mutations in the INPP5E gene cause Joubert syndrome 1 characterized by mental retardation, retinal dystrophy and truncal obesity." (PMID 33808286, 2021). "Mutations in inositol polyphosphate 5-phosphatase (INPP5)E are associated with Joubert syndrome and Bardet-Bedi syndrome, which result in retinal degeneration." (PMID 32540927, 2021). "Mutations in INPP5E result in Joubert syndrome, a rare disorder characterized by deformation of the midbrain, retinitis pigmentosa, renal cysts, and polydactyly." (PMID 32540927, 2021). "Previous results have indicated that mutations in Inpp5e lead to neural malformations, including Joubert syndrome (JBTS), Behr syndrome and micropenis (MORM) syndrome." (PMID 34093381, 2021). "Defects in oculocerebroretinal syndromes of Lowe (OCRL) phosphatase are associated with glaucoma, and mutations in inositol polyphosphatase (INPP5E) are associated with Bardet-Bedi and Joubert syndrome, which leads to retinal degeneration." (PMID 33921658, 2021). "Joubert syndrome, which is an autosomal recessive disorder, has a mutation in the INPP5E gene (613037) on chromosome 9q34." (PMID 32489745, 2020). "To this end, we focused on the Tectonic 2 (TCTN2) gene which is crucial for ciliary transition zone architecture and which, like INPP5E, is mutated in Joubert Syndrome." (PMID 32840212, 2020). "The INPP5E mutations that cause Joubert syndrome diminish the 5-phosphatase activity of the protein, whereas MORM syndrome mutations result in a protein with phosphatase activity but that abnormally localizes to cilia." (PMID 31413155, 2019). "A Type IV inositol polyphosphate 5-phosphatase, INPP5E, has been localized to the cilium and mutations in INPP5E have been found in Joubert syndrome, which presents with retinitis pigmentosa, kidney cysts, and mental developmental delays." (PMID 23805271, 2013). "Previously inositol phosphatases OCRL and INPP5E have been found to be implicated in Lowe syndrome and Joubert syndrome, respectively." (PMID 23805271, 2013). "In Joubert syndrome, upon loss of INPP5E, cilia become shorter and HH signaling increases." (PMID 40483459, 2025). "To understand AURKA’s role in regulating renal cyst development we conditionally deleted the gene in mouse models of Autosomal Dominant PKD (ADPKD) and Joubert Syndrome, caused by Polycystin 1 (Pkd1) and Inositol polyphosphate-5-phosphatase E (Inpp5e) mutations respectively." (PMID 38191531, 2024). "The 5-phosphatases, OCRL and INPP5E, are mutated in Lowe and Joubert syndrome, respectively." (PMID 32540927, 2021). "At least two neurological disorders with PCH have already been observed in combination with a disorder of sexual development: PCH7 due to bi-allelic variants in TOE1 (OMIM # 614969, *613931) and Joubert syndrome 1 due to bi-allelic variants in INPP5E (OMIM # 213300, *613037)." (PMID 33168985, 2021). "Besides pifo, a mutation in Inositol polyphosphate-5-phosphatase E (INPP5E) has been reported in patients with Joubert syndrome." (PMID 26840332, 2016).